GSK3A (glycogen synthase kinase 3 alpha)
Diseases named in the same sentence as GSK3A in open-access papers (continued):
Sharing a sentence is not in itself a finding about the gene and the disease.
cancer (continued). "Moreover, we include recent experimental evidence that reveals how the dysfunction of GSK3α is related to pathological conditions in ND and cancer." (PMID 33339170, 2020). "The following sections emphasize the prominent role that GSK3α plays in different types of cancer." (PMID 33339170, 2020). "Particularly intriguing was the prediction that GSK3α is a putative ALK substrate in cancer cells." (PMID 29555900, 2018). "GSK3α/β plays a crucial role in a variety of regulatory networks for HNSCC cancer progression as it drives proliferation or migration and thus GSK3 could serve as an interesting target for clinical drug development." (PMID 29963225, 2018). "Treatment with 10 μM MK-2206, an Akt inhibitor widely used in the clinical trials for cancer indicated a significant decrease in the expression of phosphorylated Akt, Phosphorylated GSK-3α/β, claudin-5, ZO-1 and ZO-2 protein levels compared to DMSO-treated controls in HLECs." (PMID 29755115, 2018). "Indeed, mutant KRas-dependent human cancer cells undergo apoptosis only when both GSK3α and GSK3β are knocked down simultaneously." (PMID 30514931, 2018). "Few investigations have addressed the role of GSK3A in cancer cells so far." (PMID 24984063, 2014). "Moreover, genes like CCR4 and GSK3A highlighted in this study are already candidate targets for therapy in other cancers." (PMID 21884569, 2011). "Furthermore, GSK-3 has multiple functions beyond suppression of Wnt signaling, and it is also possible that complete loss of GSK3A/B is not compatible with cancer cell viability, despite the clear vitality of Gsk3a/b DKO mESCs." (PMID 37759479, 2023). "It will be of future interest to investigate whether RASTR plays a role in mediating cellular fitness upon the knockdown of RPs in GSK3α-inhibited cancer cells, and if so, how exactly the downregulation of distinct RPS/RPL proteins regulates proteostasis capacity in these cells." (PMID 37686063, 2023). "Importantly, GSK-3α inhibition improved cancer surveillance by human NK cells in vivo." (PMID 33918810, 2021). "In summary, the central regulatory role of GSK3α/β in macrophage viability and immunometabolic function suggests that it may be a viable target to treat a variety of diseases and disorders related to cancer and inflammation." (PMID 33672232, 2021). "To further investigate this hypothesis, we used SMARTpool siGENOME small interfering RNAs (siRNAs) to deplete KRas and GSK3α/β from a panel of eight mutant KRas-harboring human cancer cell lines and then determined the effects of silencing these genes on apoptosis and viability." (PMID 30514931, 2018). "Although a PAS stain was not available in the protein atlas database, which would determine whether the matrix networks were positive for glycogen, a stain against glycogen synthase (GSK3A) was available and showed that the chains of cancer cells significantly expressed this enzyme." (PMID 29162797, 2017). "Therefore, very little is known about GSK3A role in cancer cells." (PMID 24984063, 2014). "In other types of cancers, isoliensinine tends to regulate upstream apoptotic pathways, such as AKT/GSK3α and MAPK/JNK." (PMID 40732297, 2025). "In mammals, it is present in two isoforms (GSK-3α and GSK-3β) and has relevant roles in many diseases, including Alzheimer’s disease, type 2 diabetes, inflammation, and cancer." (PMID 34885651, 2021). "However, recent evidence suggests that the selective inhibition of GSK3α and GSK3β activity may shed light on the role of each paralog and also open new avenues for developing specific therapeutic strategies for each type of cancer." (PMID 33339170, 2020). "Significant suppression of GSK3α/β phosphorylation in TNBC cells by fisetin and quercetin is consistent with the role of this protein kinase in cancer cell motility and metastasis." (PMID 31898540, 2020).
cancer (continued). "Our data revealed a strong inactivation of GSK3α/β in permanent HNSCC cell lines as well as in solid HNSCC, which has also been reported for other types of cancers." (PMID 29963225, 2018). "Additionally, GSK-3α is involved in various signaling pathways beyond PI3K/AKT, including the regulation of NF-κB, which plays a role in inflammation and cancer progression." (PMID 39156976, 2024). "Besides the well-characterised modulators of CDK1, our analysis highlights a novel potential role for MYO3A, GSK3A and GRK6 kinases, whose expression profile is highly correlated with CDK1 itself and its modulators across cancer tissues." (PMID 37898722, 2023). "Thus, the dominant regulation of the activating ligands by GSK-3α, as shown here, highlights the differential roles of GSK-3α and GSK-3β in cancer surveillance by NK cells, further supporting the notion of isoform-specific functions of GSK-3." (PMID 33918810, 2021). "This was consistent with our study showing that GSK3α/β depletion did not affect the efficiency of NHEJ in cancer cells." (PMID 33589588, 2021). "In order to evaluate AML sensitivity to GSK3α/β gene silencing, we analyzed the publically available shRNA screening data in Project DRIVE16, which contains the cell viability data following shRNA gene silencing of various genes across 384 cancer cell lines." (PMID 30679640, 2019). "Gsk3a inhibitors were effective in 12 of 72 inhibitors (16.667%) across three screens, suggesting Gsk3a is not critical for cancer cell survival in U23674." (PMID 31208434, 2019). "Importantly, GSK3α is now known as a novel CREB-target gene that promotes the viability of cancer cells and NF-κB-dependent gene transcription of TERT, indicating a reciprocal regulation between CREB and GSK3α." (PMID 29434603, 2018). "Since GSK3 activity is inhibited by Akt-mediated phosphorylation at Serine 21 and Serine 9 in two different isoforms namely GSK3α and GSK3β respectively, scientists believed that activation of GSK3 may likely suppress cancer progression." (PMID 25714023, 2015). "Therefore, it is likely that GSK3α/β-dependent phosphorylation of BOK may be one of the important mechanisms that control BOK expression and function in cancer cells." (PMID 29156771, 2017). "This advocates that irrespective of its expression levels, GSK3α, in addition to GSK3β should be taken into confidence while targeting GSK3 for cancer therapy." (PMID 25714023, 2015). "No significant equivalent sensitivity was noted for other cancer metabolic drugs such as PIK3CA (GDC0941 and AZD6482), GSK3A/B (SB 216763) inhibitors and PRKAA2 (AICAR and metformin) agonists." (PMID 24699711, 2014).
infection (11 papers, 2015 to 2025). The state of being infected such as from the introduction of a foreign agent such as serum, vaccine, antigenic substance or organism. "Moreover, the exogenous expression of GSK3A restored the susceptibility of HeLa-GSK3A-KO cells to HAdV-B7 infection." (PMID 40537285, 2025). "Overexpressing both wildtype and mutations of GSK-3α/β potently increased levels of mRNA, protein, and the ratio of activated GS to GS and significantly attenuated intracellular Mtb infection upon 48 and 72 h of infection." (PMID 35095838, 2021). "Her results showed that GSK3A expression significantly increased following HAdV-B7 infection; overexpression of GSK3A promoted viral replication, while its knockdown or knockout inhibited replication." (PMID 39992112, 2025). "Our findings provide a foundation for exploring GSK3A as a potential target for antiviral therapies against HAdV-B7 infections." (PMID 40537285, 2025). "In summary, GSK3A is a proviral host factor for HAdV-B7 infection, with its phosphorylation of viral proteins." (PMID 40537285, 2025). "On the other hand, the phosphorylation levels of GSK-3α/β were increased at earlier periods of infection (30 and 45 days)." (PMID 34303703, 2021). "Infection of WT, GSK3α−/−, or GSK3β−/− cells with WT Salmonella resulted in a similar amount of Y705-phosphorylated STAT3, which was no longer detected in lysates from GSK3α/β−/− cells, despite similar total STAT3 levels." (PMID 31862381, 2020). "A marked reduction of GSK3α/β kinase activity from 60 to 120 min post infection led to a gradual decrease in the relative abundance of phosphorylated glycogen synthase at Ser641." (PMID 29434603, 2018). "Data in this work indicate that the relative abundance of phospho-GSK3α was higher than that of phospho-GSK3β during the infection of BEC with viable S. aureus, as we have previously reported." (PMID 29434603, 2018). "At initial stages of infection, a gradually decreasing fraction of GSK3α and in minor proportion GSK3β remains activated, implying an indirect correlation between the amount of GSK3α in its active form and the expression of IL-8." (PMID 29434603, 2018). "In conclusion, during the first 60 min of BEC infection by S. aureus, GSK3α activity maintains its inhibitory influence on CREB phosphorylation at Ser133, limiting the formation of CREB-CBP complex and leaving CBP free to interact with NF-κB." (PMID 29434603, 2018). "We found both that PEDV affected GSK-3α/βphosphorylation in late stages of infection and the phosphorylation of GSK-3α/β was regulated by Akt." (PMID 27560518, 2016). "After 24 h infection with equivalent viral titres of each GSK3 adenovirus the levels of GSK3α were increased 5-6-fold and the levels of GSK3β doubled (n.b. the recombinant GSK3β has a Myc tag which means it has a slightly higher molecular mass than endogenous GSK3β)." (PMID 38479223, 2024). "We observed that Akt inhibition did not affect NF-κB p65 phosphorylation level at 40 min of infection; however, at 120 min, a slight increase in phospho-p65 was observed, suggesting that GSK3α/β activity promotes NF-κB phosphorylation at later stages of infection." (PMID 29434603, 2018). "The time course of BEC infected with S. aureus showed that the phosphorylation of GSK3α (Ser21) and GSK3β (Ser9) increased significantly after 40 min of infection, GSK3α phosphorylation (~8-fold compared with control) being higher than GSK3β (~2.5-fold compared with control)." (PMID 29434603, 2018). "However, GSK3α activity inhibition at later stages of infection favors CREB activation that leads to IL-10 expression." (PMID 29434603, 2018). "In line with this thought, we found that complete GSK3α inhibition at 120 min post infection led to a substantial reduction of the NF-κB-CBP complex compared with the abundance of this complex observed at 40 min post infection and a high increase in CREB-CBP interaction." (PMID 29434603, 2018).
infection (continued). "Thus, in response to heat-killed Yp treatment, GSK-3α shows increased phosphorylation at S21 residue during early post infection times (1 and 4 h post infection), which is known to inactivate GSK-3α." (PMID 25762983, 2015). "Notably, GSK3A appeared to uniquely promote HAdV-B7 infections." (PMID 40537285, 2025). "Genetic validation using gene silencing and CRISPR knockout of both GSK3α and GSK3β in THP-1 cells, demonstrate the role of both genes in controlling early infection of Mtb in these monocytic like macrophages." (PMID 39175770, 2024). "CRISPR inactivation of either GSK3α or GSK3β independently in THP-1 cells (left group) confirmed these findings, showing about 50% and 30% reduction of intracellular Mtb 72 h post infection, respectively." (PMID 39175770, 2024). "Infection or treatment with P-4423632 did not affect the phosphorylation level of other reactive GSK3α and β phosphosites." (PMID 39175770, 2024). "By contrast, GSK3α/β demonstrated increased activation in male hearts early after infection, but not in females." (PMID 37737732, 2023). "GSK-3α content significantly increased at 75 days of infection, but no changes were observed in GSK-3β." (PMID 34303703, 2021). "Similarly, at no point after infection were phosphorylated GSK3α/β levels different between the sexes (day 2, P = 1.0; day 7, P = 0.91; day 14, P = 0.09)." (PMID 37737732, 2023). "The expression of IL-10 increased when BECs were incubated with SB at 6 h post infection, whereas in the presence of Akt-IV, no change in IL-10 peptide compared to control was observed, indicating that active Akt (inactive GSK3α/β) was required to induce IL-10 synthesis." (PMID 29434603, 2018).
neurodegenerative disease (8 papers, 2015 to 2023). A disorder of the central nervous system characterized by gradual and progressive loss of neural tissue and neurologic function. "Collectively, this work suggests that drugs such as AZD5438 that inhibit both GSK3α/β and CDKs may confer protections to cells when they are under physiological stresses associated with the aetiology of neurodegenerative diseases such as PD and AD." (PMID 37221196, 2023). "Although the tau kinases DYRK1A and GSK3α/β play key roles in the effects of LPS in the CNS and neurodegenerative diseases such as AD, few studies have investigated the effects of calcium channel blockers on tau kinase activity in vivo." (PMID 37435081, 2023). "In neurodegenerative diseases such as AD, the activation of GSK3α not only participates in the process of APP hydrolysis to form Aβ but also regulates the phosphorylation of tau." (PMID 36533181, 2022). "This specific function should be considered in future studies of neurodegenerative diseases and neuropsychiatric conditions that originate from suboptimal levels of GSK3α/β activity." (PMID 26207897, 2015). "Emerging evidence has shown a role for GSK-3α in brain functioning and neurodegenerative disease." (PMID 32581704, 2020). "GSK-3 is a highly conserved serine/threonine protein kinase comprised of two isoforms such as GSK-3α and GSK-3β, which are glycogen synthase regulators and involved in several neurodegenerative diseases." (PMID 27552165, 2016).
metabolic disorders (3 papers, 2021 to 2025). "Dysregulation of GSK3α/β has been implicated in several metabolic disorders." (PMID 34394077, 2021). "Importantly, pharmacological inhibition of GSK3α improves insulin sensitivity and glucose tolerance in diet-induced diabetic mice, highlighting GSK3α as a therapeutic target for metabolic disorders." (PMID 36445308, 2023).
neurological disorder (2 papers, 2017 to 2025). "As more is learned about differential regulations and actions of GSK3α and GSK3β, it may be possible to devise more specific therapeutic interventions for a number of neurological disorders associated with GSK3 signaling." (PMID 29234272, 2017). "In the brain, both GSK3α and GSK3β are expressed, and disruption of GSK3 signaling has been implicated in a number of neurological diseases, such as schizophrenia, major depression, bipolar disorder, and neurodegenerative diseases." (PMID 29234272, 2017).
psychiatric diseases (2 papers, 2009 to 2015). "While GSK3α is usually important in neurodegenerative and psychiatric diseases GSK3β is fundamental in the inflammatory response caused by bacterial components." (PMID 26200352, 2015). "Taken together, these data support a role for the GSK-3α gene in CNS functioning and possible involvement in the development of psychiatric disorders." (PMID 19925672, 2009).
bacterial infections (1 paper, 2015). "This suggests that although GSK3β is the isoform generally associated with the inflammatory response to bacterial infections, as reported by several authors, GSK3α may also play an important role in this process through the regulation of pro-inflammatory cytokine expression." (PMID 26200352, 2015).
infectious disease (1 paper, 2021). A disorder directly resulting from the presence and activity of a microbial, viral, or parasitic agent in humans. "Therefore, the dysregulation of GSK-3α/β has been linked to diverse diseases, including infectious disease, cancer, Alzheimer’s disease, bipolar disorder, and diabetes." (PMID 35095838, 2021). "In infectious disease, on one hand, GSK-3α/β activation can be detrimental to the host response against Francisella tularensis LVS infection by restraining inflammatory cytokine response." (PMID 35095838, 2021).
kidney disease (1 paper, 2019). "We show here that in contrast to previous research indicating that podocyte‐specific genetic knockout of GSK3β has a beneficial effect in models of kidney disease; podocyte ablation of GSK3α is not similarly protective." (PMID 31825015, 2019).
GSK3A also shares sentences with these, for which no sentence is quoted: gastric cancer (4 papers); brain cancer (2); Glucose intolerance (2); myelodysplastic syndrome (2); Parkinson disease (2); acute liver failure (1); adenocarcinoma (1); adenoid cystic carcinoma (1); amyotrophic lateral sclerosis (1); basal cell carcinoma (1); benign tumor (1); cancer of the nervous system (1); cardiac diseases (1); cardiovascular disease (1); Chronic Heart Failure (1); colorectal adenocarcinoma (1); CTNNB1 syndrome (1); Diamond-Blackfan anemia (1); endometrial cancer (1); endometriosis (1); epithelioid sarcoma (1); Hypertension (1); Impaired glucose tolerance (1); lung fibrosis (1); mood disorder (1); myeloid leukemia (1); Neurodegeneration (1); oral squamous cell carcinoma (1); osteoporosis (1); Senile plaques (1).
A further 2 diseases each share a sentence with GSK3A in 1 paper.